PTCD3 (pentatricopeptide repeat domain 3)
Description:
Mitochondrial RNA-binding protein that has a role in mitochondrial translation.
Synonyms: MRP-S39; FLJ20758; DKFZp666K071; mS39; COXPD51
Tractability: Small molecule: a structure with a bound ligand is known. Antibody: its Gene Ontology location is reachable by antibodies, with high confidence. PROTAC: ubiquitination databases record sites on it; its protein half-life has been measured.
Target class: Other cytosolic protein
Gene: Protein-coding gene on chromosome 2 (86,106,223 to 86,142,157, forward strand). Ensembl gene ENSG00000132300.
Subcellular location: Mitochondrion
Subcellular location (Human Protein Atlas): Mitochondria
Pathways (Reactome):
Metabolism of proteins: Mitochondrial ribosome-associated quality control; Mitochondrial translation elongation; Mitochondrial translation initiation; Mitochondrial translation termination
Gene Ontology:
Molecular function: protein binding; ribosomal small subunit binding; RNA binding; rRNA binding
Biological process: mitochondrial translation
Cellular component: mitochondrial matrix; mitochondrion; mitochondrial inner membrane; mitochondrial small ribosomal subunit
Genetic constraint (gnomAD): Loss-of-function variants: 65 observed, 70.57 expected, observed/expected ratio (o/e) 0.92, 90% interval 0.75 to 1.13. The upper end of that interval is the gene's LOEUF score, 1.13, which puts it in group 4 of 6, group 1 being the genes least tolerant of losing a copy. Missense variants: 657 observed, 652.93 expected, observed/expected ratio (o/e) 1.01, 90% interval 0.94 to 1.07. Synonymous variants: 238 observed, 224.94 expected, observed/expected ratio (o/e) 1.06, 90% interval 0.95 to 1.18.
Gene-disease validity (ClinGen):
ClinGen rates the evidence that PTCD3 causes each of these diseases.
Leigh syndrome (autosomal recessive): Limited. A progressive neurological disease defined by specific neuropathological features associating brainstem and basal ganglia lesions.
Homologues: Orthologues: chimpanzee PTCD3 (99% identical), macaque PTCD3 (90% identical), dog PTCD3 (81% identical), pig PTCD3 (79% identical), guinea pig PTCD3 (77% identical), rat Ptcd3 (76% identical), mouse Ptcd3 (74% identical), tropical clawed frog ptcd3 (47% identical), zebrafish ptcd3 (47% identical), Drosophila melanogaster CG4679 (29% identical), Caenorhabditis elegans let-630 (19% identical).
Diseases named in the same sentence as PTCD3 in open-access papers:
PTCD3 is named in the same sentence as 18 diseases in open-access papers, as found by Europe PMC text mining. Sharing a sentence is not in itself a finding about the gene and the disease. The quoted sentences say what the papers report.
lymphoma (3 papers, 2016 to 2022). A malignant (clonal) proliferation of B- lymphocytes or T- lymphocytes which involves the lymph nodes, bone marrow and/or extranodal sites. "Knockdown of Ptcd3 or other mitochondrial ribosomal proteins (Mrps5 or Mrps27) decreased both expression of mitochondrion-encoded proteins and respiration rates, and was detrimental to Myc-driven lymphomas." (PMID 27635472, 2016). "Recently, PTCD3 (also known as MRPS39) was shown to be critical for the maintenance of Myc-driven lymphomas." (PMID 36233293, 2022). "Recently, PTCD3, also named MRPS39, was demonstrated to be critical in the maintenance of Myc-driven lymphoma." (PMID 34772924, 2021). "Recently, a critical role of MRPS39, also called PTCD3, was demonstrated in Myc-driven lymphoma." (PMID 34772924, 2021).
Leigh syndrome (2 papers, 2021 to 2024). "Low ATP hits that increased cytosolic ROS without affecting mitochondrial ROS included PTCD1, a mitochondrial ribosomal assembly factor and AD-associated risk gene, and PTCD3, a related mitochondrial ribosomal protein in which mutations can cause Leigh syndrome." (PMID 38207075, 2024). "mS39 (MRPS39, PTCD3)—The heterozygous variants c.415 − 2A>G and c.1747_1748insCT (p.Phe583Serfs*3) in mS39 were identified in a single individual with Leigh syndrome." (PMID 33917098, 2021).
optic atrophy (2 papers, 2023 to 2024). A disorder characterized by loss of optic nerve fibers. "We hypothesise that pathogenic missense variants of PTCD3 cause a milder form of oxidative phosphorylation deficiency accompanied by symptoms of optic atrophy, ataxia, spasticity, paralysis and polyneuropathy." (PMID 39544688, 2024).
B-cell lymphomas (1 paper, 2016). "Here, we present an in vivo reverse-genetic screen targeting a set of 241 Myc-activated mRNAs in mouse B-cell lymphomas, unraveling a critical role for the mitochondrial ribosomal protein (MRP) Ptcd3 in tumor maintenance." (PMID 27635472, 2016).
emphysema (1 paper, 2022). "PTCD3 levels were decreased in smokers and individuals with emphysema compared to nonsmokers as detected by RT-PCR." (PMID 35884802, 2022). "We did not detect any significant changes in PTCD1 and PTCD3 protein levels between controls and emphysema by Western blotting." (PMID 35884802, 2022).
Encephalopathy (1 paper, 2024). Encephalopathy is a term that means brain disease, damage, or malfunction. "Currently, there are three familial cases reported with Leigh or Leigh‐like syndrome (progressive early necrotising encephalopathy) due to loss‐of‐function variants of the PTCD3, which cause reduced expression of the PTCD3 protein and altered mitochondrial respiration." (PMID 39544688, 2024).
MELAS (1 paper, 2022). "The PTCD3 (related to mitochondrial translation) and MICU2 (a mitochondrial inner membrane protein) were not expressed at all in MELAS patients." (PMID 36254078, 2022).
Sepsis (1 paper, 2025). Sepsis is defined as life-threatening organ dysfunction caused by a dysregulated host response to infection. "PTCD3, a mitochondrial ribosomal protein, was associated with both immunosuppressive and immunostimulatory factors in sepsis, linking mitochondrial dysfunction to immune dysregulation." (PMID 41194984, 2025). "Given that mitochondrial dysfunction is a hallmark of ferroptosis, the association between PTCD3 and immune cell regulation may provide a novel mechanism by which ferroptosis contributes to immune suppression and organ dysfunction in sepsis patients." (PMID 41194984, 2025). "In conclusion, our study indicates the potential importance of key genes including CDC25B, DPP7, FBXO31, and PTCD3 in the shared pathogenesis of sepsis and T2DM." (PMID 41194984, 2025). "Differential gene expression and co-expression network analyses identified five key genes—CDC25B, DPP7, FBXO31, PTCD3, and CNPY2—that play critical roles in immune response and cellular regulation in sepsis and T2DM." (PMID 41194984, 2025). "In the GSE65682 sepsis dataset, these genes showed high discriminative ability, with AUC values reaching 0.970 (CDC25B), 0.965 (FBXO31), and 0.967 (PTCD3)." (PMID 41194984, 2025). "Related patterns were observed for FBXO31, PTCD3, and CNPY2, which also demonstrated significant correlations with multiple immune cell subsets, underscoring their collective involvement in sepsis immunopathology." (PMID 41194984, 2025). "Further refinement by intersecting these genes with previously identified DEGs yielded five candidate genes: CDC25B, DPP7, FBXO31, PTCD3, and CNPY2, These genes emerged as promising biomarkers for both T2DM and sepsis, warranting further investigation into their functional roles." (PMID 41194984, 2025).
mitochondrial disease (3 papers, 2021 to 2024). "To date, there are only two examples of the discovery of novel mitochondrial disease gene encoding proteins within a mitoribosomal subunit – MRPS34 and PTCD3/MRPS39 – through proteomic studies." (PMID 33586140, 2021). "Proteomic studies have identified two novel genes related to mitochondrial diseases: MRPS34 and PTCD3." (PMID 39323625, 2024).
cancer (2 papers, 2018 to 2023). A tumor composed of atypical neoplastic, often pleomorphic cells that invade other tissues. "Among the 102 feature genes, eight genes (MYLK, GADD45A, ACADM, UQCR11, TST, PTCD3, SOD1, CD151) were significantly enriched in the cancer hallmark of adipogenesis." (PMID 36905391, 2023).
tumor (2 papers, 2016 to 2023).
PTCD3 also shares sentences with these, for which no sentence is quoted: Ataxia (1 paper); epilepsy (1); Nystagmus (1); ovarian carcinoma (1); polyneuropathy (1); Respiratory insufficiency (1); syndromic epilepsy (1).